NDRG1 (N-myc downstream regulated 1)
Diseases named in the same sentence as NDRG1 in open-access papers (continued):
Sharing a sentence is not in itself a finding about the gene and the disease.
prostate carcinoma (continued). "NDRG1 was shown to inhibit metastasis by decreasing cell–cell and cell–matrix adhesion in AT6.1 rat prostate cancer cells and to inhibit metastasis to lungs without affecting primary tumor growth in a SCID mouse model." (PMID 26431493, 2015). "Therefore, the proteolytic cleavage of NDRG1 protein may not be just prostate-cancer specific." (PMID 23634903, 2013). "We, hence, conclude that VPA might function more effectively on metastatic prostate cancer than on non-metastatic prostate cancer and that the anticancer effect of VPA on prostate cells is, in part, mediated by the induction of NDRG1." (PMID 26692161, 2015). "Furthermore, BTF3, NDRG1 and HINT1, in quantitative co-localization studies appear capable of discriminating between biochemical relapse and non-relapse prostate cancer." (PMID 24386364, 2013).
pancreatic cancer (57 papers, 2006 to 2026). "Low NDRG1 expression is associated with poor prognosis in patients with pancreatic cancer, and NDRG1 overexpression has been demonstrated to inhibit pancreatic tumor growth." (PMID 40378957, 2025). "In other cancer types, such as colorectal cancer, pancreatic cancer, and esophageal squamous cell carcinoma, low NDRG1 expression was significantly associated with worse overall survival, suggesting tissue-specific functions of NDRG1." (PMID 39736699, 2024). "In contrast, evidence has elucidated that NDRG1 is associated with anti-oncogenic and anti-metastatic effects in breast, prostate, colorectum, and pancreatic cancers." (PMID 35795037, 2022). "During metastasis, tumor growth and invasion require angiogenesis, and overexpression of NDRG1 is associated with a decrease in pro-angiogenic factors, resulting in a decrease of angiogenesis in pancreatic cancer." (PMID 33912215, 2021). "Clinically important, the data provided suggest that NDRG1 may offer a powerful diagnostic tool for the grading of pancreatic cancers, whereas better characterising of the protein may help to decide on how aggressive the adjuvant therapy should be planned." (PMID 16832411, 2006). "It was demonstrated that the upregulation of NDRG1 in pancreatic cancer cells modulated the ER stress response by increasing the expression of ER calcium-binding chaperones, such as calreticulin and calnexin." (PMID 40378957, 2025). "Recent studies discovered a role for NDRG1 in the regulation of the Wingless (WNT)/β-catenin signaling pathway via its ability to upregulate protein kinase Cα (PKCα) in pancreatic cancer cell types." (PMID 40378957, 2025). "It has been described by our laboratory that NDRG1 expression is involved in the negative regulation of autophagy at the initiation level in pancreatic cancer cells." (PMID 40378957, 2025). "This metabolic alteration toward anabolism after NDRG1 expression in pancreatic cancer cells was also confirmed by studies examining key enzymes involved in fatty acid and cholesterol synthesis." (PMID 40378957, 2025). "Overexpression of NDRG1 in pancreatic cancer cells results in MIG6 stabilization, with MIG6 half-life increasing from 1.6 ± 0.2 h under control conditions to 7.9 ± 0.4 h after NDRG1 overexpression." (PMID 40378957, 2025). "The results showed that NDRG1 was upregulated in glioma, cervical squamous cell carcinoma, mixed renal cell carcinoma, pancreatic cancer, and other tumors." (PMID 39668822, 2024). "In pancreatic cancer, NDRG1 suppressed TGF-β and NF-κB signaling, thereby enhancing membrane E-cadherin expression." (PMID 39092227, 2024). "The metastasis suppressor, N-myc downstream regulated gene-1 (NDRG1), inhibits pro-oncogenic signaling in pancreatic cancer (PC)." (PMID 38815861, 2024). "NDRG1 localisation in hepatocellular carcinoma, and prostate, colon and pancreatic cancer has been shown to have functional implications." (PMID 40530439, 2024). "In fact, novel NDRG1-inducing thiosemicarbazones demonstrate pronounced activity against pancreatic cancer models in vitro and in vivo and also other tumors." (PMID 38815861, 2024). "In the colon, prostate, and pancreatic cancer cells, overexpression of NDRG1 restored the co-localization of E-cadherin and β-catenin at the cell membrane, which facilitates the formation of the adherens complex." (PMID 37345116, 2023). "A truncated form of NDRG1 with a deletion in the N-terminal domain was found in several prostate and pancreatic cancer cell lines." (PMID 35563887, 2022). "In fact, NDRG1 phosphorylation at Ser330 and THr346 was shown to suppress the NF-κB signalling pathway in pancreatic cancer cells." (PMID 36497221, 2022). "In the pancreatic cancer cell model, NDRG1 overexpression was induced via treatment with DpC and Dp44mT and resulted in a decrease in NF-κB activation and as well as its downstream targets Snail, Slug and, ZEB1, which suppress E-cadherin expression." (PMID 36497221, 2022).
pancreatic cancer (continued). "NDRG1 is an oncogenic signaling disruptor that plays a key role in multiple cancers, including aggressive pancreatic tumors." (PMID 34572031, 2021). "Regulation of EGFR is at least partially mediated by NDRG1, which is in accordance with the results observed in pancreatic carcinoma." (PMID 35008802, 2021). "In colon, prostate, breast and pancreatic cancer, NDRG1 suppresses tumour proliferation and metastasis." (PMID 32537867, 2020). "In pancreatic cancer, NDRG1 acts as an anti-tumor factor by repressing proliferation and impeding invasion and migration of the proteins p-STAT3, PI3K, p-AKT, MMP2, MMP9." (PMID 31205821, 2019). "N-myc downregulated gene-1 (NDRG1) which exhibits tumor suppressor-like activity in pancreatic cancer is an example of a gene coregulated by MALAT-1/EZHZ." (PMID 29389953, 2018). "And the activity of EGFR as a key receptor tyrosine kinase was shown to be regulated by NDRG1 in human pancreatic cancer cells." (PMID 29467385, 2018). "In pancreatic cancer cells it has been shown that the metastasis suppressor, N-myc downstream regulated gene-1 (NDRG1) inhibits NEDD4 expression." (PMID 28423617, 2017). "In MIAPaCa-2 pancreatic cancer cells, NDRG1 over-expression also increased PTEN levels and decreased p-AKT and p-mTOR levels." (PMID 26125440, 2015). "Subsequent studies reported a reduction in tumor microvascular density, invasion depth and histopathological grading, with a corresponding increase in overall survival rates for pancreatic cancer patients with higher levels of NDRG1 expression." (PMID 26431493, 2015). "Two reports have suggested that phosphatase treatment of cell lysates depletes phosphorylated NDRG1 detected by Western-blot analysis in HUVECs (human endothelial umbilical vein endothelial cells) and MIAPaCa-2 pancreatic cancer cells." (PMID 23634903, 2013). "In support, studies using the same anti-NDRG1 antibody to the C-terminal identified two immunoreactive NDRG1 species in a range of human pancreatic cancer cell lines." (PMID 23634903, 2013). "NDRG1 is regarded as a metastasis suppressor gene in cancers of the pancreas, colon, breast, cervix, ovaries and prostate." (PMID 23634903, 2013). "With regard to other types of cancer, a high NDRG1 expression level has shown lower invasive and metastatic potential in colorectal, prostate and pancreatic cancer." (PMID 24260043, 2013). "Our previous study demonstrated that NDRG1 suppresses tumor growth and angiogenesis of pancreas cancer through NDRG1 driven attenuation of NF-κB signaling pathway." (PMID 22844455, 2012). "Cellular hypoxia is a characteristic feature of pancreatic tumours and is generally known to act as potent inducer of NDRG1 expression." (PMID 16832411, 2006). "The data presented in this study demonstrate that regardless of the hypoxic environment, there is a selective expression of NDRG1 in the pancreatic tumour cells." (PMID 16832411, 2006). "As pancreatic cancer is characterised as a hypoxic tumour, we next questioned why there was negligible NDRG1 expression in the undifferentiated tumour cells." (PMID 16832411, 2006). "By immunohistochemistry, we observed that NDRG1 was highly expressed in well-differentiated cells of pancreatic cancer, whereas the poorly differentiated tumour cells were negative." (PMID 16832411, 2006). "NDRG1 is strongly induced by hypoxia, one of the key characteristics of pancreatic cancer, thus our first goal was to establish NDRG1 as a tumour marker for this aggressive malignancy." (PMID 16832411, 2006). "In pancreatic cancer cell types, NDRG1 silencing induces translocation of membrane E-cadherin and β-catenin into nuclei, leading to the activation of the pro-oncogenic WNT pathway, which includes cyclin D1, which promotes cell cycle progression and proliferation." (PMID 40378957, 2025).
pancreatic cancer (continued). "In fact, these later studies demonstrated that genetically expressed NDRG1 suppressed basal and hypoxia-induced autophagy at both the initiation and degradation stages and sensitized pancreatic cancer cells to lysosomal membrane permeabilization induced by Dp44mT and its redox-active copper complex." (PMID 40378957, 2025). "Similarly, in pancreatic cancer, NDRG1 was demonstrated as a metastasis suppressor via attenuating WNT, transforming growth factor β (TGF-β) and NF-κB signaling." (PMID 40378957, 2025). "Conversely, NDRG1 appears to act as a tumor suppressor in prostate and pancreatic cancers." (PMID 38987777, 2024). "Indeed, NDRG1 suppresses metastasis in prostate, breast, colon, and pancreatic cancers; however, it promotes tumor progress in liver, esophagus, cervical, and aggressive triple-negative breast cancer." (PMID 38983911, 2024). "N-Myc downstream-regulated gene-1 (NDRG1), a tumor-suppressor gene, inversely correlates with tumor progression in a variety of tumors, including pancreatic cancer, and NDRG1 enhances the expression of NEDD4L in pancreatic cancer cells, which plays a role in degrading carcinogenic pSMAD2L." (PMID 38027016, 2023). "NDRG1 can upregulate E-cadherin expression in pancreatic cancer cells." (PMID 36293154, 2022). "Additionally, both phosphorylation and proteolytic cleavage of NDRG1, shown in HCC, prostate, colon, and pancreatic cancer cells have been associated with different localization implications." (PMID 36497221, 2022). "However, the present results also stand in contrast to a recent study of miR-1469 as a promoter of cellular invasion in pancreatic cancer cell lines via inhibition of metastasis suppressor gene NDRG1 with subsequent activation of NF-κB." (PMID 34469478, 2021). "In recently, research found that regulation of NDRG1 could inhibit HGF and IGF-1signal, reduce cell migration and enhance the drug sensitive in pancreatic cancer, and NDRG1 expression could be repressed by miR-1469-5p, regulating NF-ƙB pathway activity." (PMID 34099022, 2021). "The tumor-suppressive functions of NDRG1 were further elucidated in pancreatic carcinoma." (PMID 35008802, 2021). "Analysis of changes in gene expression after MALAT-1 knockdown shows that this lncRNA represses several tumor suppressor-like genes including N-myc downregulated gene-1 (NDRG-1), a tumor suppressor in pancreatic cancer that is also corepressed by EZH2 (a PRC2 complex member)." (PMID 29389953, 2018). "However, no methylation of the CpG island of the NDRG1 promoter was found in pancreatic cancer cells, suggesting an indirect mechanism for NDRG1 de-repression by these treatments." (PMID 23874837, 2013). "Indeed, both over-expression and phosphorylation of NDRG1 modified angiogenic gene expression in pancreatic cancer cells through down-regulation of the NF-κB pathway." (PMID 24265802, 2013). "However, in pancreatic cancer, NDRG1 is highly expressed in well-differentiated cells, while the poorly-differentiated tumor cells show no NDRG1 expression." (PMID 24260043, 2013). "Furthermore, N-Myc downstream-regulated 1(NDRG1) and DNA protein cross-link (DpC) reduced cross-talk between pancreatic cancer cells and pancreatic stellate cells by inhibiting β-catenin and YAP/TAZ nuclear localization and promoting DKK1, a Wnt inhibitor, in pancreatic cancer cells." (PMID 36550571, 2022). "N-myc downregulated 1 (NDRG1) was a tumor suppressor, which has been reported in various studies; it could attenuate NF-kB and TGF-b pathways in pancreatic cancer cells, and downregulated NDRG1 was related to increased proliferation, invasion, and migration of digestive cancers." (PMID 33790969, 2021). "More recently, NDRG1 has been demonstrated to inhibit the bi-directional crosstalk between PC and pancreatic stellate cells, which is required for desmoplasia formation in pancreatic tumors, one of the key characteristics of PC that makes it resistant to current treatments." (PMID 34572031, 2021).
pancreatic cancer (continued). "Importantly, NDRG1 alters the expression of a variety of transcription factors and genes involved in ribosome and protein synthesis and reduces the expression of cathepsin C, a molecule which has roles in invasion, in pancreatic cancer." (PMID 26125440, 2015). "Similarly, NDRG1 (N-myc downstream regulated gene-1) could also regulate NEDD4 expression in pancreatic cancer cells." (PMID 24657926, 2014). "Thus far, NDRG1 expression has yet to be studied in pancreatic cancer." (PMID 16832411, 2006). "Among them, the mRNA levels of ADM, C4orf3, ERO1L, FUT11, BNIP3L, NDRG1, KCTD11, SLC2A1, and P4HA1 were increased in pancreatic cancer tissues compared to adjacent pancreatic tissues from TCGA and GTEx database." (PMID 34221996, 2021). "This discrepancy may be due to the ability of NDRG1 to regulate autophagy after incubation with iron chelators, which would decrease recycling of nutrients to facilitate apoptotic cell death, as well as differences in the cell types, that is, pancreatic cancer cells versus OS cells." (PMID 28906492, 2017). "In these later cell types, GSK3β expression or activation was either not affected by NDRG1 expression in prostate and colon adenocarcinoma cancer cells or downregulated and inactivated by NDRG1 expression in pancreatic cancer cells." (PMID 40378957, 2025). "Similarly, in PANC-1 pancreatic cancer cells, trichostatin A (TSA), another histone deacetylase inhibitor, highly upregulates the mRNA and protein expression of NDRG1 to induce differentiation." (PMID 34077484, 2021). "However, NDRG1 potentially reduced GLI1, a key driver of pancreatic cancer, to suppress cell migration mediated by pancreatic stellate cells." (PMID 34965023, 2021). "Treatment with 5-Aza-2′-deoxycytidine and Trichostatin A enhanced NDRG1 protein expression in pancreatic cancer cell lines, and again, there was no methylation of CpG island in the NDRG1 promoter." (PMID 26692161, 2015). "Interestingly, NDRG1 was found to inhibit the process of angiogenesis by negatively regulating critical pro-angiogenic factors, such as IL-8, MMP-9 and VEGF1, in pancreatic cancer." (PMID 26431493, 2015). "In addition, NDRG1 inhibits the expression of VEGF and MMP-9, and suppresses the growth and angiogenesis of pancreatic cancer cells." (PMID 24269992, 2013). "It is possible that the antibody utilized by these latter investigators detects both the phosphorylated and non-phosphorylated NDRG1 proteins on Western-blot analysis of human MIAPaCa-2 pancreatic cancer cell line and renal cancer cell lines, 786-O and Caki-1." (PMID 23634903, 2013). "However, we were unable to detect MIG-6, which has been reported to be responsible for NDRG1-mediated EGFR downregulation in pancreatic carcinoma cell lines (data not shown), which illustrates the need for further study of the means of action." (PMID 35008802, 2021). "Therefore, we suggest that the determining factor of NDRG1 expression in pancreatic cancer is not hypoxia, but rather the differentiation status of the tumour." (PMID 16832411, 2006).
hepatocellular carcinoma (42 papers, 2013 to 2025). A malignant tumor that arises from hepatocytes. "NDRG1 has been shown to suppress metastasis in pancreatic, ovarian and colorectal cancers, whereas in lung, cervical and hepatocellular cancers, NDRG1 has been associated with tumour progression." (PMID 40530439, 2024). "The amplification or overexpression of NDRG1 causes problems in hepatocellular carcinoma, esophageal cancer, and lung cancer." (PMID 27148394, 2016). "In addition, in some tumor-types (e.g., hepatocellular carcinoma), NDRG1 was associated with more aggressive phenotypes and a poorer prognosis." (PMID 26418878, 2015). "Although NDRG1 primarily exhibits anti-cancer and anti-metastasis functions, it has also been shown to promote cancer in certain cancers such as gastric cancer and hepatocellular carcinoma." (PMID 39980566, 2025). "For example, lactate has been acquainted to drive senescence-resistant hepatocellular carcinoma through lactylation of histone H2B at K58 on N-myc downstream-regulated gene 1 (NDRG1)." (PMID 41345704, 2025). "This conclusion is supported by observations that β-catenin protein levels and nuclear accumulation decrease after suppressing NDRG1 expression in hepatocellular carcinoma cells." (PMID 40378957, 2025). "A study showed that the inhibition of NDRG1 suppresses hepatocellular carcinoma growth and reactivates senescence signaling." (PMID 38329430, 2024). "Yet other mechanisms that mediate the activity of NDRG1 have been reported examining Huh7 and HepG2 hepatocellular carcinoma cells, where direct binding of NDRG1 to GSK-3β prevented its binding to β-catenin." (PMID 38815861, 2024). "To explore the mechanism by which NDRG1 promotes the proliferation and metastasis of hepatoma cells, we detected ROS expression levels by flow cytometry." (PMID 37208604, 2023). "NDRG1 can enhance the interaction between fibroblasts and tumor cells, leading to the development of hepatocellular carcinoma." (PMID 37517087, 2023). "In hepatocellular carcinoma, siRNA-mediated reduction of NDRG1 sensitized cancer cells to doxorubicin-induced apoptosis." (PMID 37298315, 2023). "In hepatocellular carcinoma, the expression of NDRG1 was positively correlated with T follicular helper, Th2, and NK cells and negatively correlated with plasmacytoid dendritic cells and Th17 cells." (PMID 37345116, 2023). "Multicolor immunofluorescence results demonstrated a significant elevation and co-localization of CD206 and NDRG1 expression in hepatocellular carcinoma tissues compared to paracancerous tissues." (PMID 38235128, 2023). "Multifactorial Cox regression of 11 prognostic genes resulted in seven independent risk genes affecting the prognosis of patients with hepatocellular carcinoma, namely ENO1, NDRG1, NPM1, H2AX, IL33, MT3 and TXNRD1." (PMID 38097352, 2023). "Our multicolor immunofluorescence results have revealed a significant elevation and co-localization of CD206 and NDRG1 in hepatocellular carcinoma tissues." (PMID 38235128, 2023). "Under hypoxic conditions, HIF-1α was essential for NDRG1 transcription in Hepatocellular carcinoma (HCC) cells." (PMID 36497221, 2022). "Conversely, in hepatocellular carcinoma, knocking down NDRG1 expression resulted in the induction of apoptosis, further reinforcing the context dependent role and tissue specific outcomes." (PMID 36497221, 2022). "Some studies revealed that NDRG1 is highly expressed in hepatocellular carcinoma and cervical cancer and interrupts many metastasis-associated processes, including epithelial-mesenchymal transition (EMT)." (PMID 33375117, 2020). "The N-myc downstream regulated gene 1 (NDRG1) is significantly associated with advanced tumor stages and poor survival of hepatocellular carcinoma (HCC), thereby implicating it as a potential target for HCC treatment." (PMID 26359353, 2015). "Furthermore, NDRG1 directly interacts with GSK3β to participate in the regulation of β-catenin degradation in hepatocellular carcinoma cells." (PMID 40378957, 2025).